SKA3 (spindle and kinetochore associated complex subunit 3)
Diseases named in the same sentence as SKA3 in open-access papers (continued):
Sharing a sentence is not in itself a finding about the gene and the disease.
liver cancer (6 papers, 2019 to 2022). An epithelial or non-epithelial malignant neoplasm that arises from the liver. "Overexpression of SKA3 has been detected in a variety of tumor types including lung, rectal, cervical, and liver cancer." (PMID 34993016, 2021). "Several studies indicated that SKA3 regulates cell cycle transition and promotes cell proliferation in cervical, colorectal, and liver cancers." (PMID 34572901, 2021). "In this study, we found that the expression level of SKA3 in liver cancer tissues and cells was significantly higher than that in normal liver tissues and cells, suggesting that SKA3 was highly expressed in liver cancer." (PMID 31804459, 2019). "SKA3 expression is enhanced in liver cancer tissue compared to normal liver tissue, and inhibiting SKA3 expression considerably weakens the proliferation of liver cancer cells." (PMID 35546682, 2022). "Thus, SKA3 can served as an independent biomarker for prognosis of patients with liver cancer." (PMID 31804459, 2019). "In this study, bioinformatic analysis found that SKA3 has an important relationship with CDK2, and after knocking down SKA3, CDK2 was the major downregulated protein, which explained the G2 arrest of liver cancer cells after knocking down SKA." (PMID 31804459, 2019).
prostate carcinoma (6 papers, 2018 to 2024). A carcinoma that arises from epithelial cells of the prostate gland. "Other studies showed that overexpression of SKA1 and SKA3 was related to cancer aggressiveness in several other cancers, including non-small cell lung cancer, prostate cancer, bladder cancer, gastric cancer, colorectal cancer and adenoid cystic carcinoma." (PMID 29928475, 2018). "However, little is known regarding the probable mechanism of SKA3, particularly in terms of prostate cancer (PCA) progression." (PMID 36266657, 2022). "Aberrant SKA3 expression has been observed in prostate cancer and colorectal cancer." (PMID 33817174, 2019).
bladder cancer (5 papers, 2018 to 2025). "In conclusion, SKA3 can influence the prognosis of bladder cancer patients and is associated with immune infiltration." (PMID 35546682, 2022). "A recent study reported that high SKA3 expression is associated with poor clinical outcomes and muscle-invasive bladder cancer progression, and promotes bladder cancer cell proliferation by accelerating G2/M transition." (PMID 35546682, 2022). "Another significant aspect of our research indicates that SKA3 expression is associated with various levels of immune infiltration in bladder cancer." (PMID 35546682, 2022). "Additionally, SKA3 expression was found to be positively associated with enhanced M2 macrophage and T helper (Th) 2 cell infiltration in bladder cancer." (PMID 35546682, 2022). "Thus, upregulation of SKA3 is associated with bladder cancer development." (PMID 34572901, 2021). "In bladder cancer and other tumors, patients with high SKA3 expression levels had worse overall survival (OS) (p = 0.016), disease-specific survival (DSS) (p = 0.00004), and disease-free survival (DFS) (p = 0.032)." (PMID 35546682, 2022). "The immune infiltration state in tumor microenvironment (TME) can affect patient prognosis, and previous results indicate that SKA3 overexpression was connected to deleterious prognosis in bladder cancer patients." (PMID 35546682, 2022). "The current study investigated the expression mode, prognostic effect, and functional role of SKA3 in different tumors, particularly bladder cancer using numerous databases, comprising TIMER, GEPIA, HPA, UALCAN, PrognoScan, and Kaplan–Meier Plotter." (PMID 35546682, 2022). "Our findings reveal a potential practical function of SKA3 in bladder cancer and emphasize a machine-made foundation of SKA3 influences on M2 macrophage and Th2 cell polarization in tumor microenvironment." (PMID 35546682, 2022). "Following that, the relevance of SKA3 expression to immune infiltration level in bladder cancer was evaluated using TIMER." (PMID 35546682, 2022). "Our study implies that SKA3 contributes to M2 macrophage and Th2 cell polarization by acting as an oncogene in bladder cancer." (PMID 35546682, 2022). "The preceding investigation indicated that SKA3 influences patient prognosis via its interaction with immune cell infiltration in bladder cancer." (PMID 35546682, 2022). "We observed marked decreases in the proliferation of both bladder cancer cell lines in response to SKA3 knockdown." (PMID 34572901, 2021). "A significant proportion of the SKA3 siRNA-transfected bladder cancer cells had shifted to G2/M and fewer of them were in G0/G1 than the control." (PMID 34572901, 2021). "Our data also showed that SKA3 promotes bladder cancer cell proliferation by accelerating G2/M transition." (PMID 34572901, 2021). "Knockdown experiments confirmed that SKA3 promotes bladder cancer cell proliferation by accelerating G2/M transition." (PMID 34572901, 2021). "In the present study, we performed systematic transcriptome analyses on bladder cancer patient cohorts and identified SKA3 as a putative accurate prognostic marker for progression." (PMID 34572901, 2021). "RT-qPCR showed that SKA3 was significantly downregulated in bladder cancer cells transfected with SKA3 siRNAs, and knockdown efficiency was approximately 90–95%." (PMID 34572901, 2021). "To determine the functional roles of SKA3 in bladder cancer cells, we used small interference RNA (siRNA)-induced knockdown to suppress SKA3 expression in the bladder cancer cell lines 5637 and T24." (PMID 34572901, 2021). "We analyzed the cell cycle by flow cytometry to elucidate the mechanisms by which SKA3 regulates bladder cancer cell proliferation." (PMID 34572901, 2021). "In addition, in GEPIA and HPA databases, SKA3 was highly expressed in bladder cancer relative to normal bladder tissue." (PMID 35546682, 2022).
bladder cancer (continued). "Additionally, we confirmed SKA3 expression in bladder cancer using immunohistochemical staining in HPA database." (PMID 35546682, 2022). "Consequently, we defined if SKA3 expression was connected to immune infiltration level by examining their correlation in bladder cancer using TIMER." (PMID 35546682, 2022). "In addition, SKA3 expression in bladder cancer was significantly correlated with M2 macrophage markers, including MRC1 and CD163, and Th2 cell markers, including CCR3 and IL-4." (PMID 35546682, 2022). "SKA3 was closely correlated with immune checkpoint genes in most tumors, including bladder cancer." (PMID 35546682, 2022). "In particular, SKA3 may promote bladder cancer growth and metastasis by influencing the differentiation of M2 macrophage and Th2 cells." (PMID 35546682, 2022). "Increased cytoplasm SKA3 staining was found in 21 of 25 cases of bladder cancer." (PMID 35546682, 2022). "In addition, RNA-seq of SKA3 from TCGA bladder cancer dataset and GTEx dataset revealed that SKA3 expression was obviously higher in bladder cancer tissue (n = 404) than in normal bladder samples (n = 28)." (PMID 35546682, 2022). "Immunohistochemistry was further used to validate the expression of SKA3 gene in bladder cancer." (PMID 35546682, 2022). "In the future, functional studies should be conducted to determine whether a combination therapy comprising SKA3 inhibition plus BCG can effectively prevent bladder cancer progression." (PMID 34572901, 2021). "Furthermore, scRNA-seq analysis of bladder cancer revealed that SKA3 was upregulated in certain epithelial cell subpopulations with a high probability of proliferation." (PMID 34572901, 2021). "Moreover, Kaplan–Meier curves of time to progression in various external cohorts from public databases verified that SKA3 is closely related to bladder cancer clinical pathology and progression." (PMID 34572901, 2021). "Consequently, high SKA3 expression is an independent risk factor for bladder cancer patients, rather than a protective factor." (PMID 35546682, 2022). "SKA3 might be a novel biomarker for evaluating prognosis and immune infiltration in bladder cancer." (PMID 35546682, 2022). "Therefore, SKA3 can represent a valuable prognostic biomarker for bladder cancer." (PMID 35546682, 2022). "Our functional study showed that SKA3 knockdown inhibited cancer cell colony formation and cell cycle progression from G2 to M. SKA3 upregulation in the tumor microenvironment accelerates G2/M transition, promotes cell proliferation, and induces bladder cancer progression." (PMID 34572901, 2021). "Hence, SKA3 is a viable predictive marker for bladder cancer progression and its inhibition could constitute part of a novel therapy that improves the prognosis of this disease." (PMID 34572901, 2021). "Overall, SKA3 may exacerbate bladder cancer tumors by affecting the cell cycle." (PMID 34572901, 2021). "Additionally, SKA3 was predicted to be involved in nuclear division, mitotic nuclear division, mitotic sister chromatid segregation, humoral immune response, and cell chemotaxis.The high expression of SKA3 in bladder cancer was further verified using immunohistochemistry." (PMID 35546682, 2022). "Concurrently, SKA3 expression was positively correlated with the expression level of Th2 cell markers (IL-4 and CCR3) in bladder cancer." (PMID 35546682, 2022). "However, the role of SKA3 in bladder cancer remains unknown." (PMID 35546682, 2022). "Moreover, SKA3 expression was positively correlated with gene markers of M2 macrophage such as MRC1 and CD163 in bladder cancer." (PMID 35546682, 2022). "Increased cytoplasm SKA3 staining was found in 21 of 25 cases of bladder cancer, and the results indicated that the protein expression of SKA3 in bladder cancer tissues was significantly higher than that in noncancerous tissues." (PMID 35546682, 2022).
bladder cancer (continued). "An independent sample t-test of SPSS 26.0 was used to compare the IRS between the two groups, and the results indicated that the protein expression of SKA3 in bladder cancer tissues was significantly higher than that in noncancerous tissues (P < 0.05)." (PMID 35546682, 2022). "We selected the SKA3 gene for further analysis as its prognostic potential in bladder cancer patients has never been investigated." (PMID 34572901, 2021). "Furthermore, scRNA-seq data revealed high SKA3 and MKI67 expression in specific epithelial cell subpopulations of bladder cancer tissue." (PMID 34572901, 2021). "However, the correlation between SKA3 and immune infiltration of bladder cancer has not been studied." (PMID 35546682, 2022). "However, the roles of SKA3 in bladder cancer have not been elucidated." (PMID 34572901, 2021).
colorectal cancer (5 papers, 2018 to 2022). A primary or metastatic malignant neoplasm that affects the colon or rectum. "On the contrary, high SKA3 expression in colorectal cancer was associated with favorable survival." (PMID 35546682, 2022). "Previous studies reported that SKA3 expression was enhanced during development from colorectal adenoma to colorectal cancer within individual patients." (PMID 33817174, 2019). "An early study showed that SKA3 correlates with the progression of colorectal cancer, leading to higher chromosome instability (CIN) in tumors." (PMID 30459531, 2018). "In addition, depletion of SKA3 presents an inhibitory effect on cell growth and induces apoptosis in colorectal cancer cells." (PMID 33817174, 2019).
gastric cancer (5 papers, 2018 to 2025). A primary or metastatic malignant neoplasm involving the stomach. "In vitro studies showed that silencing SKA3 expression inhibited the proliferation, migration, invasion, adhesion and epithelial-mesenchymal transition of gastric cancer." (PMID 35295342, 2022). "SKA3 may be the initiating factor to promote the progression of gastric cancer." (PMID 35295342, 2022). "The effects of SKA3 and DUSP2 on the proliferation, migration, invasion, adhesion, and epithelial-mesenchymal transition of gastric cancer were studied in vitro and in vivo." (PMID 35295342, 2022). "Mechanistically, SKA3 negative regulates the tumor suppressor DUSP2 and activates the MAPK/ERK pathway to promote gastric cancer." (PMID 35295342, 2022). "However, the role of SKA3 in gastric cancer has not been studied." (PMID 35295342, 2022).
colorectal adenoma (4 papers, 2016 to 2022). An adenoma that arises from the colon or rectum. "Moreover, SKA3 overexpression causes colorectal adenoma to progress to cancer, whereas knocking out SKA3 in colorectal adenoma cells greatly reduces cell growth rate, induces G2/M block, and reduces cell migration and invasion." (PMID 35546682, 2022). "Moreover, SKA3 overexpression was associated with chromosomal instability, while interference with SKA3 in colorectal adenoma cells induced G2/M arrest, reduced migration and invasion abilities, and increased apoptosis." (PMID 34845974, 2021).
lung carcinoma (4 papers, 2020 to 2022). "Previous work revealed that SKA3 mRNA expression was elevated and correlated with poor survival outcomes in lung cancer patients." (PMID 34059086, 2021). "Further, reduced expression of SKA3 can significantly inhibit the metastasis of lung cancer cells." (PMID 34806315, 2022). "Similarly, it has been reported that high SKA3 expression promotes lung cancer cell proliferation and predicts patient outcomes." (PMID 33224872, 2020). "We further noted that SKA3 expression was elevated in vitro LUAD cell lines (H226 and SK-MED-1 cells) compared with non-lung cancer cells (MRC-5)." (PMID 32068236, 2020). "Results showed that the mRNA expression of BIRC5, SHCBP1, CCNA2, SKA3 and GINS1 in LUAD and LUSC tissues were all significantly higher than that in normal tissues, whereas only BIRC5 and CCNA2 protein expression in lung cancer tissues were much higher than those in the normal lung tissues." (PMID 34806315, 2022).
cholangiocarcinoma (3 papers, 2023 to 2025). A carcinoma that arises from the intrahepatic biliary tree (intrahepatic cholangiocarcinoma) or from the junction, or adjacent to the junction, of the right and left hepatic ducts (hilar cholangiocarcinoma). "RNA-seq was used to find out the differentially expressed pathways in cholangiocarcinoma proliferation under hypoxia regulated by SKA3." (PMID 37821935, 2023). "RNA-sequencing was performed and verified that SKA3 enhanced fatty acid synthesis by up-regulating the expression of key fatty acid synthase, thus promoting cholangiocarcinoma cell proliferation under hypoxic conditions." (PMID 37821935, 2023). "Functional experiments in vitro and in vivo showed that hypoxia-induced SKA3 promoted cholangiocarcinoma cell proliferation." (PMID 37821935, 2023). "However, the roles of SKA3 in cholangiocarcinoma (CCA) and the underlying mechanisms remain unclear." (PMID 37821935, 2023). "SKA3 was chose to be the target gene because of its remarkably upregulation and unknown function in cholangiocarcinoma in TCGA datasets, GSE107943 datasets and our sequencing results." (PMID 37821935, 2023). "Under hypoxic conditions, SKA3 recruits PARP1 to bind with HIF-1α, thereby enhancing USP7-mediated deubiquitination of HIF-1α, promoting the proliferation and fatty acid synthesis of cholangiocarcinoma cells." (PMID 39944823, 2025). "Although previous studies have reported that SKA3 interacted with PARP1/HIF-1α to promote cholangiocarcinoma proliferation, our findings did not reveal a direct interaction between SKA3 and HIF-1α in LUAD." (PMID 41298345, 2025).
glioma (3 papers, 2021 to 2024). A benign or malignant brain and spinal cord tumor that arises from glial cells (astrocytes, oligodendrocytes, ependymal cells). "Moreover, the overexpression of SKA1 and SKA3 was significantly associated with poor prognosis of patients with gliomas." (PMID 35095717, 2021). "Furthermore, high mRNA levels of SKA1 and SKA3 complex were significantly associated with shorter OS of patients with glioma." (PMID 35095717, 2021). "We found a significant overexpression of the mRNA levels of SKA1, SKA2, and SKA3 in patients with glioma patients." (PMID 35095717, 2021). "It has been observed that there is a statistically significant overexpression of the mRNA levels of SKA1, SKA2, and SKA3 in tumors as compared to normal tissues of patients with glioma included in the UALCAN database using Wilcoxon rank sum tests (p < 0.01)." (PMID 35095717, 2021). "More likely, SKA1 and SKA3 played a more crucial role compared to SKA2 in those identified pathways for gliomas." (PMID 35095717, 2021). "The mRNA levels of SKA1, SKA2, and SKA3 were significantly upregulated in gliomas." (PMID 35095717, 2021). "Interestingly, the expression of SKA1 and SKA3 was negatively correlated with OS in WHO G3 gliomas (p < 0.001 and P = 0.002, respectively)." (PMID 35095717, 2021). "This could be an indication that SKA1 and SKA3 are better prognostic biomarkers for gliomas." (PMID 35095717, 2021). "A significant overexpression of the mRNA levels of SKA1 and SKA3 was found in WHO Grade 4 (G4) as compared to G3 and G2 gliomas." (PMID 35095717, 2021). "Based on the results, there are much more related genes identified with SKA1 and SKA3, but less genes for SKA2 in gliomas." (PMID 35095717, 2021). "Furthermore, the K-M curve analysis of SKA complex in patients with gliomas included in the GEPIA database demonstrated that the patients with gliomas who have higher expressions of SKA1 and SKA3 tend to have shorter OS than those with lower expression (p < 0.01)." (PMID 35095717, 2021). "However, the clinical value of SKA complex (SKA1, SKA2, and SKA3) as a prognostic biomarker in gliomas has not been investigated fully." (PMID 35095717, 2021). "Higher expression of SKA1 and SKA3, but not SKA2, was significantly correlated with shorter overall survival of patients with glioma." (PMID 35095717, 2021).
laryngeal squamous cell carcinoma (3 papers, 2020 to 2025). A squamous cell carcinoma that arises from the larynx. "Here, SKA3 is identified as an oncogene in laryngeal squamous cell carcinoma (LSCC), and high levels of SKA3 are closely associated with malignant progression and poor prognosis." (PMID 33106477, 2020). "Besides, SKA3 overexpression facilitated proliferation and chemoresistance of laryngeal squamous cell carcinoma (LSCC) by reprogramming PLK1–AKT axis-mediated glycolytic metabolism, which was also related to the unfavorable prognosis of LSCC patients." (PMID 34845974, 2021). "Additionally, as a tumor metabolic regulatory gene, SKA3 can inhibit the ubiquitination and degradation of polo-like kinase 1 (PLK1) protein, resulting in the upregulation of glycolytic enzymes and enhanced glycolysis in laryngeal squamous cell carcinoma." (PMID 41298345, 2025).